PPM1D (protein phosphatase, Mg2+/Mn2+ dependent 1D)
Diseases named in the same sentence as PPM1D in open-access papers (continued):
Sharing a sentence is not in itself a finding about the gene and the disease.
brainstem gliomas (10 papers, 2016 to 2024). "To this end, we use murine models to demonstrate that endogenous truncation of murine Ppm1d together with histone and Pdgfra mutations is sufficient to drive de novo brainstem glioma formation, as is exogenous expression of truncated human PPM1D (PPM1Dtr)." (PMID 35105861, 2022). "PPM1D mutations assembled in H3F3A-mutated malignant brainstem gliomas, and high intratumoral CD8+ T cell density was less common in the H3F3A-mutated tumors." (PMID 34470916, 2021). "PPM1D truncating mutations have been reported in brainstem gliomas, but the frequency rate varies between different studies." (PMID 32555164, 2020). "Truncating mutations in the final exon of PPM1D (p.457_465del and p.R552X) were found in two DCGs; these mutations were previously reported as gain-of-function mutations in brainstem glioma harboring H3F3A K27M." (PMID 28852847, 2017). "Because PPM1D alterations have been a target of drug development, novel therapeutic opportunities may be available in the future for cerebellar and brainstem gliomas with PPM1D truncating mutation or fusion." (PMID 28852847, 2017). "Therefore, PPM1D mutations predicted the limited benefits of radiotherapy on brainstem glioma patients." (PMID 29137285, 2017). "PPM1D mutations and PD-L1 expression appeared to predict whether the brainstem glioma patients would benefit from postoperative radiotherapy." (PMID 29137285, 2017). "PPM1D alterations therefore appear to be present both in brainstem gliomas and less frequently in supratentorial gliomas." (PMID 29802247, 2018). "Other mutations that have been reported in adult brainstem glioma, such as mutations in PDGFRA, PIK3CA, and PPM1D, are also potentially targetable with drugs that are either already commercially available or in development." (PMID 27556016, 2016). "In contrast, C-terminal truncation of Ppm1d by sgPpm1dexon6 was sufficient to generate fully penetrant brainstem gliomas, with all mice developing neurological symptoms (17/17) with a median survival of 44 days, representing a significantly shorter latency (P < 0.0001 log rank Mantel–Cox test)." (PMID 35105861, 2022).
colon carcinoma (10 papers, 2015 to 2025). "For example, the high expression of PPM1D is associated with poor prognosis for the esophageal squamous cell carcinoma patients, whereas its silencing inhibits colon cancer cell proliferation." (PMID 35682850, 2022). "We have identified various types of somatic frameshift and/or nonsense mutations in the last exon of PPM1D in the colon tumors in cohorts of CRC patients from three countries and similar mutations were also found in publicly available databases." (PMID 31659152, 2019). "Based on our results we propose that inhibition of PPM1D may represent a promising strategy for improving efficacy of 5-FU in colon cancer treatment, especially in patients with MMR-deficient tumors located in caecum and ascending colon." (PMID 31659152, 2019). "This is supported by the demonstration that Ppm1d-deficient mice show a delayed onset of mammary gland tumor development whereas an accelerated onset of tumors is evident in mice overexpressing PPM1D and ERBB2 in the mammary gland as well as reduced survival of APCmin mice developing colon cancer." (PMID 34771656, 2021). "Whereas truncated PPM1D may be insufficient to fully transform ISCs and drive tumorigenesis of otherwise normal cells, in genetically sensitized background it promoted growth of colon tumors." (PMID 31659152, 2019). "Cancer cell lines carrying truncated PPM1D (including U2OS and HCT116 cells) are heterozygotes, and also colon carcinoma samples do not contain both mutant alleles." (PMID 32927737, 2020).
diffuse intrinsic pontine glioma (10 papers, 2019 to 2025). A neuroglial tumor that arises from the middle portion of the brain stem. "Functionalized macrophage exosomes with panobinostat and PPM1D‐siRNA are constructed for targeted therapy of diffuse intrinsic pontine glioma (DIPG) with PPM1D mutation." (PMID 35585670, 2022). "Mutations in the Protein Phosphatase PPM1D are oncogenic in certain cancers including diffuse intrinsic pontine glioma (DIPG)." (PMID 31439867, 2019). "As an example, the combination of lentivirus-mediated silencing of PPM1D and temozolomide chemotherapy has been shown to eradicate malignant glioma, and PPM1D inhibitors can enhance the anti-proliferative and pro-apoptotic effects of ionizing radiation in diffuse intrinsic pontine glioma." (PMID 37360159, 2023). "In addition, the researchers developed a nano delivery system based on functionalized macrophage sEVs targeted with heliostat and PPM1D-siRNA for PPM1D mutant diffuse intrinsic pontine glioma, with higher administration efficiency and better therapeutic efficacy than free drugs." (PMID 38951882, 2024). "PPM1D is implicated in regulating the chemosensitivity of OVCA cells, and in diffuse intrinsic pontine glioma (DIPG), PPM1D inhibition was found to sensitize PPM1D-mutant DIPG cells to PARP inhibitor treatment." (PMID 36583171, 2022).
osteosarcoma (10 papers, 2016 to 2025). A usually aggressive malignant bone-forming mesenchymal neoplasm, predominantly affecting adolescents and young adults. "Furthermore, BCAS3, in conjunction with PPM1D, may be implicated in the initiation, progression, and metastasis of osteosarcoma." (PMID 40636370, 2025). "To identify the substrates of PPM1D, we metabolically labeled human osteosarcoma (U2OS) cells with amino acids in cell culture (SILAC)." (PMID 36060052, 2022). "PPM1D has been found to be modulated by miR-499a-5p and miR-499a-5p downregulation followed by PPM1D upregulation in osteosarcoma." (PMID 35087589, 2022). "Furthermore, TRPM2-AS may exacerbate osteosarcoma malignancy by acting as a molecular sponge for the miR-15b-5p/PPM1D axis." (PMID 40636370, 2025).
breast tumors (9 papers, 2007 to 2025). "Indeed, the copy number of PPM1D, the gene that encodes Wip1, positively correlates with C-to-T mutation load in primary human breast tumors." (PMID 30558184, 2018). "We had previously determined the DNA copy number levels within the centre of the 17q23 amplicon (at the PPM1D gene locus) in a set of 146 primary breast tumours by using formalin-fixed, paraffin-embedded samples." (PMID 17353917, 2007). "Moreover, several studies have confirmed PPM1D amplification in breast tumors, noting that its overexpression primarily occurs in tumors with WT TP53102,103." (PMID 41345520, 2025). "Indeed, MMTV-driven overexpression of Ppm1d potentiated Erbb2-induced breast tumor development in mice." (PMID 26883108, 2016). "In addition, about one third of breast tumors with amplified PPM1D locus also contain amplification of the ERBB2/HER2 oncogene suggesting that both genes may jointly promote tumor development." (PMID 26883108, 2016). "Our results align with this, showing PPM1D amplification in about 8% of breast tumors, although this amplification is not correlated with increased gene expression across different BC subtypes." (PMID 41345520, 2025).
hepatocellular carcinoma (9 papers, 2013 to 2024). A malignant tumor that arises from hepatocytes. "The current study examined the expression and the prognostic value of PPM1D mRNA in human hepatocellular carcinoma (HCC)." (PMID 23556002, 2013). "The gene PPM1D may be associated with tumor immune cell infiltration in hepatocellular carcinoma (HCC), thus indicating that PPM1D may be a potential prognostic biomarker for cancer progression." (PMID 38074028, 2023). "However, the knowledge regarding PPM1D mRNA expression, tumor immunity, and the prognosis in hepatocellular carcinoma (HCC) is scanty." (PMID 34470916, 2021).
acute myeloid leukemia (8 papers, 2019 to 2025). Acute myeloid leukemia (AML) is a group of neoplasms arising from precursor cells committed to the myeloid cell-line differentiation. "Multiple nonsense or frame-shift mutations in the PPM1D observed in Acute Myeloid Leukemia (AML) patients spread throughout the whole exon 6 which results in many variants of the PPM1D protein with differently a sized C-terminal tail." (PMID 32927737, 2020). "Remarkably, truncating PPM1D mutations are frequently observed in therapy-induced acute myeloid leukemia (t-AML) or myelodysplastic syndrome (t-MDS) patients, which confers the ability of HSCs carrying the truncated PPM1D to escape cell death induced by chemotherapy." (PMID 37709843, 2023). "To validate the essentiality of SOD1 in PPM1D-mutant cells, we performed in vitro competitive proliferation assays in two different acute myeloid leukemia (AML) cell lines, OCI-AML2 and OCI-AML3." (PMID 38896450, 2024). "We also assessed the effects of PPM1D inhibition on previously reported human acute myeloid leukemia (AML) PDX models." (PMID 37595362, 2023). "Accordingly, irradiated Ppm1dT/+ mice commonly developed acute myeloid leukemia, which demonstrates the pathogenicity of the truncated PPM1D in t-AML patients." (PMID 37709843, 2023). "The importance of these mutations is highlighted in mutation carriers receiving chemotherapy, because HSCs carrying the truncated PPM1D show better survival and potentially may allow development of secondary cancers including acute myeloid leukemia (AML) and myelodysplastic syndrome." (PMID 31659152, 2019). "The authors’ data indicate that PPM1D is a crucial regulator of HSC fitness and that its absence or pharmacological inhibition leads to greater sensitivity of malignant cells to chemotherapy, including in acute myeloid leukemia (AML) xenografts." (PMID 37595362, 2023).
myelodysplastic syndrome (8 papers, 2018 to 2025). A clonal hematopoietic disorder characterized by dysplasia and ineffective hematopoiesis in one or more of the hematopoietic cell lines. "Patients suffering from therapy-induced malignancies (mainly t-AML and myelodysplastic syndrome) show increased frequency of truncating PPM1D mutations and we have recently reported similar phenotype in transgenic mice." (PMID 39237765, 2024). "PPM1D mutations are more commonly found in patients with therapy-related myelodysplastic syndrome than primary myelodysplastic syndrome (15% versus 3%) and are associated with shorter survival after hematopoietic stem cell transplantation." (PMID 35954328, 2022). "Only recently have PPM1D mutations been noted in patients with hematologic conditions, specifically therapy-related myelodysplastic syndrome." (PMID 30388424, 2018). "PPM1D mutations are most frequently observed in secondary therapy-related myelodysplastic syndromes (t-MDS) and in patients with bronchial and ovarian carcinoma after chemotherapy." (PMID 38162500, 2023).
gastric cancer (7 papers, 2013 to 2022). A primary or metastatic malignant neoplasm involving the stomach. "NAPRT promoter hypermethylation in cancer is frequently associated with mutations in the protein phosphatase Mg2+/Mn2+-dependent 1D (PPM1D) or isocitrate dehydrogenase 1 (IDH1) genes, as well as with the epithelial-mesenchymal transition (EMT)-subtype of gastric cancer." (PMID 35890155, 2022). "In gastric cancer, the high PPM1D mRNA expression was significant correlated with better prognosis." (PMID 34470916, 2021).
melanoma (7 papers, 2015 to 2021). A malignant, usually aggressive tumor composed of atypical, neoplastic melanocytes. "In addition, we investigated the expression level of Ppm1d mRNA in neutrophil populations in tumor-free and B16 F10 melanoma tumor-bearing WT mice." (PMID 34131120, 2021).
prostate carcinoma (7 papers, 2014 to 2025). A carcinoma that arises from epithelial cells of the prostate gland. "While PPM1D did not demonstrate expression in clinical prostate tumors, it did show protein expression in 75% (3/4) prostate cancer cell lines tested." (PMID 40405591, 2025). "However, EPB41L5 and SERINC3 had a high rank based on mutational burden and CNVs, ELOVL6 was annotated as an oncogene in prostate cancer, and PPM1H has been proposed to be an oncogene, due to its relation to PPM1D (a well-studied oncogene in breast, ovarian, and brain cancers)." (PMID 32605588, 2020).
atherosclerosis (5 papers, 2017 to 2023). A disease characterized by the build-up of fatty material and calcium deposition in the arterial wall resulting in partial or complete occlusion of the arterial lumen. "In addition to the importance of PPM1D in oncology, it was found that PPM1D played an important role in atherosclerosis, and its role was realized by regulating the formation of “foam” cells of atherosclerotic plaque." (PMID 37726289, 2023).
diffuse midline glioma (4 papers, 2021 to 2024). A diffuse glioma that arises from the midline structures of the central nervous system. "PPM1D gene was mutated in diffuse midline glioma that originated in superior and middle cerebellar peduncle, cerebral peduncle, and pons." (PMID 34257334, 2021). "Among CNS tumors, PPM1D has been found to be a good prognostic marker for diffuse midline gliomas, younger supratentorial diffuse astrocytic tumors, and oligodendroglial tumors." (PMID 37360159, 2023). "In this work, the authors utilise genomics, proteomics, and mouse models to determine the role of PPM1D in the development of diffuse midline glioma." (PMID 35105861, 2022). "While patients with diffuse midline gliomas predominantly had the histone H3 K27M mutation, additional driver mutations, such as ACVR1 and PPM1D were noted in all of the patients that were analyzed with 500 gene panel testing." (PMID 34257334, 2021).
lung adenocarcinoma (4 papers, 2014 to 2022). A carcinoma that arises from the lung and is characterized by the presence of malignant glandular epithelial cells. "PPM1D has also been shown to be a prognostic marker in patients with lung adenocarcinoma." (PMID 25009596, 2014).
serous ovarian cancer (4 papers, 2014 to 2025).
Jansen-de Vries syndrome (3 papers, 2022 to 2025). "Jansen-de Vries syndrome (JDVS) is a rare autosomal dominant neurodevelopmental disorder caused by truncating variants in exons 5 and 6 of the PPM1D gene." (PMID 40630121, 2025). "This neurodevelopmental condition is named Jansen-de Vries syndrome (JdVS, OMIM #617450) and is characterized by frameshift or nonsense mutations in the last or second-to-last exons of the PPM1D gene." (PMID 38896450, 2024).
multiple myeloma (3 papers, 2021 to 2024). "Here, we determined the presence of PPM1D gene mutations in peripheral blood cells of 75 subsequent myeloma patients in remission after first or second HDCT/ASCT." (PMID 39194701, 2024). "The rising prevalence of PPM1D gene mutations after second ASCT is reminiscent of the rising prevalence of other CHIP gene mutations in myeloma patients after ASCT." (PMID 39194701, 2024). "Here, we investigated the prevalence of PPM1D gene mutations in the peripheral blood of myeloma patients who had been treated with chemotherapy, HDCT and ASCT." (PMID 39194701, 2024). "In a cohort of 75 myeloma patients, we identified four gDNA samples with low-frequency PPM1D gene mutations, indicating a 5% prevalence." (PMID 39194701, 2024). "After several chemotherapy lines, HDCT and ASCT, the prevalence of truncating PPM1D gene mutations in the peripheral blood of myeloma patients emerged at 1.3% after the first HDCT/ASCT and 7.3% after the second HDCT/ASCT procedure." (PMID 39194701, 2024). "The survival time from initial diagnosis to disease progression and death varied significantly in the PPM1D wild-type versus PPM1D-mutated myeloma patients." (PMID 39194701, 2024). "A prevalence of 4% PPM1D gene mutations was previously reported in a targeted sequencing study on the stem cell products of myeloma patients treated by ASCT at the Dana-Farber Cancer Institute." (PMID 39194701, 2024). "Our data suggest that the occurrence of PPM1D gene mutations in peripheral blood cells correlates with inferior outcomes after ASCT in patients with multiple myeloma." (PMID 39194701, 2024). "Low-frequency PPM1D gene mutation may be causing inferior outcomes in myeloma with chromosome 1q gain, as there was an association with PPM1D gene mutations in this context." (PMID 39194701, 2024). "This environment may promote the emergence of PPM1D gene mutations or the survival of PPM1D mutated myeloma cells." (PMID 39194701, 2024). "Moreover, the presence of DNMT3A and PPM1D mutations in stem cell grafts collected in myeloma patients correlated with reduced stem cell yields and delayed platelet count recovery following ASCT associated with impaired regeneration in ASCT recipients." (PMID 39194701, 2024). "Low-frequency PPM1D gene mutations may affect treatment response to ASCT in multiple myeloma." (PMID 39194701, 2024). "Our data suggest that PPM1D gene mutation may be a predictor of inferior survival in myeloma patients treated with HDCT/ASCT independent of age, ISS and cytogenetic risk." (PMID 39194701, 2024).
pancreatic cancers (3 papers, 2013 to 2021).